PACERR (PTGS2 antisense NFKB1 complex-mediated expression regulator RNA)
Synonyms: PACER; PTGS2-AS1
Gene: Long non-coding RNA gene on chromosome 1 (186,680,108 to 186,683,165, forward strand). Ensembl gene ENSG00000273129.
Diseases named in the same sentence as PACERR in open-access papers:
PACERR is named in the same sentence as 6 diseases in open-access papers, as found by Europe PMC text mining. Sharing a sentence is not in itself a finding about the gene and the disease. The quoted sentences say what the papers report.
breast carcinoma (1 paper, 2019). "PACERR is the antisense gene of PGTS2 (prostaglandin-endoperoxide synthase 2) that has been related to colorectal cancer and breast cancer." (PMID 31242667, 2019).
pancreatic cancer (1 paper, 2022). "Interestingly, the expression of PACERR and PTGS2 in sham group macrophages was very low and upregulated after THP‐1 co‐culture with pancreatic cancer cells." (PMID 35184402, 2022).
pancreatic ductal adenocarcinoma (1 paper, 2022). An infiltrating adenocarcinoma that arises from the epithelial cells of the pancreas. "In this study, we found the function and molecular mechanism of PACERR in TAMs to regulate pancreatic ductal adenocarcinoma (PDAC) progression." (PMID 35526050, 2022).
sarcoidosis (1 paper, 2019). Sarcoidosis is a multisystemic disorder of unknown cause characterized by the formation of immune granulomas in involved organs. "In addition, several genetic variants within or near non-HLA genes were also significantly associated with sarcoidosis: BTNL2, PTGS2/COX2, and PACERR (PTGS2 Antisense NFKB1 Complex-Mediated Expression Regulator RNA)." (PMID 31126090, 2019).
tumor (4 papers, 2022). "Here, we discovered a novel mechanism of epigenetic modulation, that results in polarization of TAMs towards pro‐tumour M2 phenotype: CTCF binds to the overlapped promoter region of PACERR and PTGS2, leading to the transcription of PACERR." (PMID 35184402, 2022). "Consistently, in the in vivo PDAC mouse models, mice injected with a mixture of PDAC cells and PACERR knockdown TAMs exhibited significantly reduced liver metastasis, validating the essential role of PACERR in inducing pro‐tumour functions of TAMs." (PMID 35184402, 2022). "Furthermore, lncRNAs, including SNHG12, PACERR and HITT, function as key regulators of tumor-associated macrophages, regulating tumor cell proliferation, invasion and migration by altering the number of M2-polarized cells and contributing to immune escape." (PMID 36601121, 2022). "Our previous data demonstrated that CTCF and PACERR bind to the promoter region of PTGS2, and both of them are indispensable for the M2 polarization and pro‐tumour functions of TAMs." (PMID 35184402, 2022). "Meanwhile the KLF12-transcribed LncRNA-PACERR interacts directly with KLF12 and the KLF12/PACERR complex activates LncRNA-PACERR transcription by recruiting EP300, thereby promoting M2 polarization and pro-tumour function in TAMs." (PMID 35526050, 2022). "The newly transcribed LncRNA PACERR interacts directly with CTCF, forming the CTCF/PACERR complex to recruit HAT EP300, resulting in increased chromatin accessibility and transcriptional activation of PTGS2, the critical driver of M2 polarization and pro‐tumour functions in TAMs." (PMID 35184402, 2022).
PACERR also shares sentences with these, for which no sentence is quoted: colorectal cancer (1 paper).